LCE2A (late cornified envelope 2A)
Description:
Precursors of the cornified envelope of the stratum corneum.
Synonyms: LEP9
Tractability: No criterion of Open Targets' tractability assessment is met for any kind of drug.
Gene: Protein-coding gene on chromosome 1 (152,698,345 to 152,699,442, forward strand). Ensembl gene ENSG00000187173.
Pathways (Reactome):
Developmental Biology: Formation of the cornified envelope
Gene Ontology:
Molecular function: protein binding
Biological process: epidermis development
Genetic constraint (gnomAD): Loss-of-function variants: 0 observed, 0.59 expected, observed/expected ratio (o/e) 0, 90% interval 0 to 1.82. That is too few expected variants to judge how well the gene tolerates losing a copy. Missense variants: 147 observed, 142.98 expected, observed/expected ratio (o/e) 1.03, 90% interval 0.9 to 1.18. Synonymous variants: 65 observed, 55.03 expected, observed/expected ratio (o/e) 1.18, 90% interval 0.97 to 1.45.
Homologues: Paralogues in human: LCE2D (92% identical), LCE2B (91% identical), LCE2C (91% identical), LCE1E (77% identical), LCE1F (77% identical), LCE5A (76% identical), LCE1D (73% identical), LCE3D (56% identical), LCE3E (54% identical), LCE3B (53% identical), LCE3C (52% identical), LCE3A (50% identical), and 8 more.
Diseases named in the same sentence as LCE2A in open-access papers:
LCE2A is named in the same sentence as 1 disease in open-access papers, as found by Europe PMC text mining. Sharing a sentence is not in itself a finding about the gene and the disease.
LCE2A shares sentences with these, for which no sentence is quoted: lung carcinoma (1 paper).